RNU6-1131P (RNA, U6 small nuclear 1131, pseudogene)
Gene: Small nuclear RNA gene on chromosome 18 (47,234,442 to 47,234,548, reverse strand). Ensembl gene ENSG00000201825.
Homologues: Orthologues: chimpanzee U6 (98% identical), macaque U6 (95% identical). Paralogues in human: RNU6-41P (90% identical), RNU6-812P (90% identical), RNU6-820P (90% identical), RNU6-1152P (89% identical), RNU6-11P (89% identical), RNU6-15P (89% identical), RNU6-166P (89% identical), RNU6-37P (89% identical), RNU6-509P (89% identical), RNU6-1122P (88% identical), RNU6-1274P (88% identical), RNU6-12P (88% identical), and 1289 more.